MSTN (myostatin)
Diseases named in the same sentence as MSTN in open-access papers (continued):
Sharing a sentence is not in itself a finding about the gene and the disease.
sarcoma (2 papers, 2019 to 2025). A usually aggressive malignant neoplasm of the soft tissue or bone. "Collectively, these findings suggest that myostatin contributes to smooth muscle differentiation in high-grade sarcomas and has potential utility as a diagnostic marker." (PMID 40868997, 2025). "Analysis of the DEG promoter activity showed that the promoter of MSTN, which encodes myostatin, was more activated in the high-grade sarcoma group, although expression levels were low in both groups." (PMID 40868997, 2025). "Beyond the role of myogenic differentiation, loss of myostatin expression may serve as a marker for sarcomas harboring potential therapeutic targets." (PMID 40868997, 2025). "In contrast, 12 of the 17 high-grade sarcoma cases (71%) showed diffusely positive myostatin staining, and two (12%) showed focal staining." (PMID 40868997, 2025). "In another case (Case 27) of high-grade sarcoma, myostatin expression changed from very focally positive to diffusely positive, and focal expression of the myogenic marker M-actin emerged following chemotherapy." (PMID 40868997, 2025). "Diffuse myostatin expression was significantly more common in sarcomas outside the LMS/PLMS group than in the LMS/PLMS group (p < 0.001)." (PMID 40868997, 2025). "Notably, two of these three myostatin-positive PLMS cases clustered together with high-grade sarcomas in the transcriptomic analysis." (PMID 40868997, 2025). "However, despite low overall expression in both groups, MSTN—a gene known to suppress muscle cell proliferation —was more strongly activated in high-grade sarcomas than in PLMSs." (PMID 40868997, 2025). "Blockade of the myostatin could also be one possible option to improve the muscular flap quality before radiation in e.g. sarcoma patients or breast patients." (PMID 31665379, 2019). "Myostatin expression, encoded by MSTN, was almost inversely correlated with the expression of myogenic markers, suggesting that it may play a role in smooth muscle differentiation in high-grade sarcomas." (PMID 40868997, 2025). "Although this study did not aim to identify specific diagnostic markers for PLMS, the absence of myostatin expression on IHC may help differentiate PLMS from other high-grade sarcomas and support its diagnosis." (PMID 40868997, 2025). "The overall myostatin positivity rate, therefore, differed between the PLMS and high-grade sarcoma groups." (PMID 40868997, 2025). "Among the 16 sarcomas outside the LMS/PLMS group, 14 expressed myostatin, with diffuse expression observed in 11 cases." (PMID 40868997, 2025). "Immunohistochemical analysis showed reduced or absent myostatin expression in PLMSs, in contrast to diffuse myostatin expression in other high-grade sarcomas." (PMID 40868997, 2025). "In general, IHC revealed that myostatin was frequently and diffusely expressed in high-grade sarcomas lacking myogenic differentiation, whereas its expression was less common in LMS and PLMSs." (PMID 40868997, 2025). "Finally, we found that the MSTN promoter was activated in high-grade sarcomas lacking both morphological and immunohistochemical evidence of smooth muscle differentiation." (PMID 40868997, 2025). "Additionally, 6 of the 10 PLMS cases exhibited a myostatin-negative/desmin-positive (diffuse or focal) phenotype, while 7 of the 17 high-grade sarcomas displayed a myostatin-positive (diffuse)/desmin-negative (or very focally positive) phenotype." (PMID 40868997, 2025). "Based on this, we hypothesized that myostatin suppresses myogenic differentiation in high-grade sarcomas lacking smooth muscle differentiation and that reduced or absent myostatin expression may be associated with myogenic marker expression in PLMSs." (PMID 40868997, 2025). "Although myostatin staining was not strong, this finding reflected the relatively low expression level of MSTN in sarcoma samples observed via CAGE, despite its comparatively higher expression in high-grade sarcomas than in PLMS." (PMID 40868997, 2025).
Telangiectasia (2 papers, 2019 to 2021). Telangiectasias refer to small dilated blood vessels located near the surface of the skin or mucous membranes, measuring between 0.5 and 1 millimeter in diameter. "Clinically, non-selective myostatin inhibitors have led to unwanted side effects, such as gingival bleeding and telangiectasias, as well as alterations in hormone levels, believed to be the result of BMP9 and Activin A inhibition, respectively." (PMID 30481286, 2019).
Urinary incontinence (2 papers, 2020 to 2024). Loss of the ability to control the urinary bladder leading to involuntary urination. "The results of these studies showed that effective PFMT and ExMI cause downregulation of myostatin concentration and an improvement in the severity of urinary incontinence in elderly women with stress UI." (PMID 32016111, 2020). "Flat magnetic stimulation reduces myostatin concentration and genital hiatus length, minimizing the severity of urinary incontinence." (PMID 39336440, 2024).
Viral infection (2 papers, 2017 to 2025). "The alterations of muscle mass seen in viral infection are associated with the expression of myostatin." (PMID 29036192, 2017). "The objective of this study was to characterize transcriptional regulation of grouper myostatin and further study the role of myostatin in immune response to viral infection." (PMID 29036192, 2017). "This study provides the novel findings of transcriptional regulation between viral infection and activation of myostatin promoter." (PMID 29036192, 2017). "Myostatin is a negative regulator of myogenesis and has been suggested to be an important factor in the development of muscle wasting during viral infection." (PMID 29036192, 2017). "According to these results, we conducted a study to investigate the effect of viral infection on myostatin promoter activity and its regulation." (PMID 29036192, 2017). "Myostatin is proposed to be a regulator that involves the immune response, because we previously reported that amount of myostatin in grouper serum was affected by viral infection." (PMID 29036192, 2017). "In addition to regulating muscle growth and development, myostatin is involved in immune response of viral infection." (PMID 29036192, 2017). "However, further investigation is needed to clarify the regulation of myostatin promoter activity during viral infection." (PMID 29036192, 2017). "However, the effect of viral infection on the transcriptional regulation of myostatin remains unclear." (PMID 29036192, 2017).
acromegaly (1 paper, 2021). Acromegaly is an acquired disorder related to excessive production of growth hormone (GH) and characterized by progressive somatic disfigurement (mainly involving the face and extremities) and systemic manifestations. "However, learning more about the association between myostatin and GH in acromegaly requires further studies." (PMID 34795636, 2021). "In the subgroup analyses of patients with acromegaly, those with IR had significantly lower serum irisin (2.80 vs. 4.18 μg/ml, p = 0.047) and myostatin (81.46 vs. 429.58 ng/L, p = 0.018) concentrations than those without IR." (PMID 34795636, 2021). "Possible negative regulation of myostatin by GH in acromegaly raises the question about its relevance in the anabolic effect of GH on muscle tissue." (PMID 34795636, 2021). "In 43 patients with acromegaly and 60 controls, serum levels of irisin, myostatin, growth hormone (GH), insulin-like growth factor 1 (IGF-1), parameters of glucose, and lipid metabolism were determined." (PMID 34795636, 2021). "In patients with acromegaly, myostatin was negatively correlated with GH, fasting insulin, and HOMA-IR." (PMID 34795636, 2021). "We are first to document the negative association of circulating myostatin levels with GH in acromegaly, which points toward GH as a negative regulator of myostatin secretion; however, this association does not appear to impact muscle mass in this disease significantly." (PMID 34795636, 2021). "Comparison of the patients with active acromegaly, controlled disease, and controls did not reveal significant differences in irisin and myostatin serum concentrations." (PMID 34795636, 2021). "The current study results indicate that in contrast to the general population, the role of myostatin is not critical for muscle mass regulation in acromegaly." (PMID 34795636, 2021). "Nevertheless, it appears that myostatin is not critical for muscle mass regulation in acromegaly." (PMID 34795636, 2021).
adrenal hypoplasia congenita (1 paper, 2022). "Myostatin expression under iron deficiency was mediated by an orphan nuclear receptor, dosage-sensitive sex reversal-adrenal hypoplasia congenita critical region on the X chromosome (DAX1)." (PMID 36139428, 2022).
Adrenal insufficiency (1 paper, 2026). Insufficient production of steroid hormones (primarily cortisol) by the adrenal glands. "In addition, adrenal insufficiency may be associated with higher levels of myostatin, a protein that negatively regulates muscle mass, as suggested in a preclinical study." (PMID 41376651, 2026).
advanced heart failure (1 paper, 2023). Patients with advanced heart failure have severe limitations, experiences symptoms even while at rest and are mostly bedbound patients. "In LV dysfunction, myostatin results overexpressed, and an increased myostatin/IGF-1 ratio has been found in subjects with ventricular dysfunction as well as in adult patients with advanced heart failure across different heart diseases." (PMID 37958492, 2023).
aging (1 paper, 2023). A developmental process that is a deterioration and loss of function over time. "We discuss the molecular properties of GDF11 as well as its closely related ligand GDF8, also called Myostatin, and their reported effects and functions in regenerative tissues and aging diseases." (PMID 38235060, 2023).
alcohol (1 paper, 2015). "Chronic alcohol has also been shown to decrease myocyte proliferation by up-regulating the expression of myostatin, a growth factor that is normally downregulated during tissue development." (PMID 26610584, 2015).
alcoholic cardiomyopathy (1 paper, 2015). A dilated cardiomyopathy which is associated with consumption of large amounts of alcohol over a period of years. "Therefore, it is no surprise that increased levels of myostatin have been observed in the myocardium of individuals suffering from alcoholic cardiomyopathy." (PMID 26610584, 2015).
alcoholic cirrhosis (1 paper, 2020). "Particularly, whether serum myostatin levels are associated with HCC development in patients with alcoholic cirrhosis remains unsolved." (PMID 33198216, 2020). "We chose patients with alcoholic cirrhosis because previous studies reported that chronic alcohol consumption induced expression of myostatin in animal models and in patients with hypertensive heart disease." (PMID 33198216, 2020). "The aim of this study was to investigate the prognostic performance of serum myostatin levels on HCC development in patients with alcoholic liver cirrhosis (ALC)." (PMID 33198216, 2020). "However, there was a lack of study to evaluate association between serum myostatin and clinical outcomes in patients with alcoholic cirrhosis." (PMID 33198216, 2020). "Although many studies suggested that chronic alcohol drinking was associated with elevated serum myostatin levels, there were no concrete data regarding prognostic performance of serum myostatin and HCC development in patients with alcoholic cirrhosis." (PMID 33198216, 2020).
allergies (1 paper, 2024). "The search did not reveal a robust relationship between MSTN variants and respiratory health, allergies, and immunity that was found for GDF11." (PMID 39237910, 2024).
angioleiomyoma (1 paper, 2025). A benign, slow-growing neoplasm that arises from the dermis or subcutaneous tissue. "Additionally, myostatin expression was absent in all 10 angioleiomyomas examined." (PMID 40868997, 2025).
aortic atherosclerosis (1 paper, 2024). A atherosclerosis that involves the aorta. "Myostatin in the vascular wall isessential for arterial aging and aortic atherosclerosis (AS) progression.Myostatin expression has been observed in neointima, new vessels, andinfiltrating cells at atherosclerotic lesion sites, with the levels increasingwith the progression of vascular injury." (PMID 39077334, 2024).
bladder disorders (1 paper, 2023). "In skeletal muscle, myostatin is known to stimulate fibrosis and, therefore, might be partly responsible for increased collagen deposits in detrusor smooth muscle tissue in bladder disorders." (PMID 36901894, 2023).
Bone Metabolism Disorder (1 paper, 2025). "This process operates in conjunction with MSTN, targeting similar pathways to ameliorate bone metabolic disorders associated with T2DM." (PMID 40136413, 2025). "Consequently, the objective of this review is to systematically synthesize and evaluate the role of MSTN in the development of bone metabolism disorders associated with T2DM as well as to elucidate the underlying mechanisms influenced by exercise interventions." (PMID 40136413, 2025). "This network regulates both MSTN expression and the levels of pro-inflammatory cytokines, ultimately contributing to the amelioration of bone metabolic disorders in patients with T2DM." (PMID 40136413, 2025). "In the context of T2DM, MSTN has been shown to exacerbate bone metabolic disorders by inhibiting the differentiation of osteoblasts and the process of bone mineralization while simultaneously promoting the differentiation and activity of osteoclasts." (PMID 40136413, 2025). "Importantly, various forms of exercise, including aerobic training (AT) and resistance training (RT), have been shown to reduce MSTN expression and ameliorate bone loss, indicating that MSTN may mediate the beneficial effects of exercise on bone metabolic disorders in T2DM." (PMID 40136413, 2025). "In the context of T2DM, there are several mechanisms that further exacerbate MSTN-mediated bone metabolism disorders." (PMID 40136413, 2025). "However, due to the intricate and multifaceted mechanical and biochemical interactions between muscle and bone, the precise mechanisms by which exercise modulates MSTN to enhance bone metabolic disorders in T2DM necessitate additional exploration." (PMID 40136413, 2025). "Exercise may alleviate bone metabolic disorders by inhibiting the overexpression of MSTN, obstructing its binding to targets, and disrupting its downstream signaling pathways." (PMID 40136413, 2025).
cervical cancer (1 paper, 2021). A primary or metastatic malignant neoplasm involving the cervix. "Contrarily, a recent publication stated that myostatin knockout induced apoptosis in human cervical cancer cells which was mediated via ROS generation." (PMID 34131275, 2021).
chronic hepatitis B (1 paper, 2020). "In previous studies performed in cirrhotic patients with chronic hepatitis B or C, serum myostatin showed a significant association with survival and HCC development." (PMID 33198216, 2020).
chronic viral hepatitis (1 paper, 2020). "First, it was a limitation that serum myostatin levels in cirrhotic patients with other etiologies of non-alcoholic steatohepatitis (NASH) or chronic viral hepatitis were not evaluated in this study." (PMID 33198216, 2020).
cognitive decline (1 paper, 2021). "Emerging pharmacological therapies for preventing muscle loss, such as antibodies against myostatin and activin receptor types IIA and IIB, might provide potential novel agents for the management of cognitive decline." (PMID 33418963, 2021).
congenital myopathies (1 paper, 2025). "GGPP depletion has also been shown to regulate MSTN and cause skeletal muscle atrophy in mice, and mutations in GGPS1, encoding a GGPP synthase, have been linked to congenital myopathies." (PMID 41373724, 2025).
cystic fibrosis (1 paper, 2013). Autosomal recessive disorder caused by pathogenic variants in the CFTR gene (cystic fibrosis transmembrane conductance regulator), which encodes a chloride and bicarbonate channel expressed in epithelial cells, and follow the diagnosis criteria. "In addition, we analyze myostatin prodomain abundance in 249 healthy individuals and in 266 patients with different diseases and for the first time demonstrate a profound upregulation of myostatin prodomain in young underweight patients with chronic pulmonary disease (mainly cystic fibrosis)." (PMID 24260393, 2013).
depression (1 paper, 2013). "Although both, MSTN and MC1R, are surrounded by significant SNPs it is obvious that they seem to lie in a sXPEHH depression compared to a little more distant SNPs." (PMID 24359457, 2013).
female infertility (1 paper, 2022). Diminished or absent ability of a female to achieve conception. "Because MSTN signaling pathways are involved in a wide range of developmental and pathological events in reproductive biology, targeting these pathways as a therapeutic strategy for overcoming female infertility may be a viable treatment option." (PMID 35780124, 2022).
gastrointestinal carcinomas (1 paper, 2009). "MTBF acts in the muscle regulation of the myostatin gene, while CDX2 is mainly expressed in the gut although its ectopic expression was also reported in cases of non-gastrointestinal carcinomas." (PMID 19523210, 2009).
glioblastoma (1 paper, 2025). The most malignant astrocytic tumor (WHO grade IV). "In human neuroepithelial and glioblastoma cells, higher levels of myostatin and activin lead to a synchronous increase in the phosphorylated Smad2 and non-phosphorylated FOXO3 levels." (PMID 40149435, 2025).
glioma (1 paper, 2026). A benign or malignant brain and spinal cord tumor that arises from glial cells (astrocytes, oligodendrocytes, ependymal cells). "Immunofluorescence confirmed upregulated expression of MSTN and TCF12 in glioma tissues and their co-localization with macrophages." (PMID 41899441, 2026).
glomerular diseases (1 paper, 2020). "The reason(s) why MSTN is more upregulated in diabetic infiltrates that in other glomerular diseases is not completely understood." (PMID 32286342, 2020). "MSTN mRNA was markedly overexpressed in DN in the glomeruli and tubulointerstitium (a ~20 to 40-fold increase vs. controls, and a ~4 to 8-fold increase vs. glomerular diseases, respectively, p < 0–05–0.01)." (PMID 32286342, 2020).
glomerulosclerosis (1 paper, 2020). A hardening of the kidney glomerulus caused by scarring of the blood vessels. "In summary, we demonstrated that the expression of MSTN is upregulated in both infiltrating and native kidney cells in patients with DN, and that it is associated with glomerulosclerosis and tubulointerstitial fibrosis." (PMID 32286342, 2020). "When MSTN immunostaining was related to individual structural kidney changes, we observed that glomerular logMSTN expression was directly associated with glomerulosclerosis (Spearman’s R = 0.61, p < 0.002)." (PMID 32286342, 2020). "The first is MSTN expression in the human kidney, its upregulation in type 2 DN, and its association with glomerulosclerosis, interstitial inflammation and fibrosis, findings that collectively suggest that MSTN, similar to other members of the TGF-β super family, is involved in kidney fibrogenesis." (PMID 32286342, 2020). "In the diabetic kidney we observed overexpression of MSTN in the glomeruli and tubulointerstitium, which correlated with glomerulosclerosis and interstitial fibrosis, respectively." (PMID 32286342, 2020). "In our study, MSTN was expressed in both infiltrating tubulointerstitial cells and native kidney cells; furthermore, MSTN expression was related to glomerulosclerosis and tubulointerstitial fibrosis, observations that suggest a role for MSTN in mechanisms mediating CKD." (PMID 32286342, 2020).